SCN1A (sodium voltage-gated channel alpha subunit 1)
Diseases named in the same sentence as SCN1A in open-access papers (continued):
Sharing a sentence is not in itself a finding about the gene and the disease.
Dravet syndrome (continued). "Mutations in the SCN1A gene coding the alpha subunit of NaV1.1 are associated with generalized epilepsy with febrile seizures, Dravet syndrome (severe myoclonic epilepsy in infancy), and inherited familial migraine." (PMID 36558088, 2022). "In Dravet syndrome, loss-of-function mutations in the SCN1A sodium channel gene are thought to promote seizures by exerting a net effect to reduce the excitability of inhibitory interneurons." (PMID 35972069, 2022). "Mosaic variants represent 5–10% of cases of cases of DEEs of genetic origin wrongly labeled as de novo, as proved in entities such as CDKL5 deficiency disorder or SCN1A-related Dravet syndrome." (PMID 35250806, 2022). "De novo LOF mutations in SCN1A are present in over 80% of patients with Dravet syndrome (DS), a severe form of childhood-onset epilepsy." (PMID 35689251, 2022). "The two probands later manifested afebrile seizures including myoclonic seizures that were similar to Dravet syndrome caused by SCN1A mutations." (PMID 35600075, 2022). "Approximately 80% of patients with Dravet syndrome carry mutations in the SCN1A gene which encodes for the α1 subunit of the type I voltage-gated sodium channel (Nav1.1)." (PMID 34980259, 2022). "Serial retrospective and double-blinded studies were conducted in 2012–2020 in patients with Dravet syndrome associated with SCN1A with results showing excellent efficacy and tolerance." (PMID 36291443, 2022). "In most cases, the de novo pathogenic variant is the cause of SCN1A Dravet syndrome and intractable childhood epilepsy with ICE-GTC." (PMID 35813387, 2022). "Seven were diagnosed with PD, one with probable MSA, and one with Dravet syndrome with SCN1A mutation." (PMID 36311955, 2022). "For example, Dravet syndrome (DS) is a highly penetrant and devastating form of childhood epilepsy caused by de novo LoF variants in SCN1A." (PMID 35983412, 2022). "The mutated SCN1A gene linked with Dravet syndrome is one of the most common gene mutations associated with SUDEP." (PMID 35893283, 2022). "Dravet syndrome (DS) is a developmental and epileptic encephalopathy associated with variants in the voltage-gated sodium channel alpha 1 subunit (SCN1A) gene in around 90% of individuals." (PMID 36176564, 2022). "Dravet syndrome is a catastrophic childhood epilepsy with early onset of seizures, caused primarily by mutations in SCN1A." (PMID 35205324, 2022). "Although most Dravet syndrome variants arise de novo, there are cases where an SCN1A variant was inherited from mildly affected parents, as well as some individuals with de novo loss-of-function or truncation mutations that presented with milder phenotypes." (PMID 35606653, 2022). "SCN1A mutations are associated with developmental and epileptic encephalopathy, Dravet syndrome, febrile seizures, and generalized epilepsy with febrile seizures plus (GEFS+)." (PMID 36011376, 2022). "To date, more than 1,800 SCN1A variants have been reported, of which <300 patients with Dravet syndrome have been mentioned for photosensitivity." (PMID 36034301, 2022). "Dravet syndrome (DS) is a developmental and epileptic encephalopathy caused by monoallelic loss-of-function variants in the SCN1A gene." (PMID 35435735, 2022). "Scn1a mutations alter the Navα1 subunit (Nav1.1) and Nav1.1 haploinsufficiency can cause Dravet Syndrome (DS)." (PMID 36686527, 2022). "Seven cases were diagnosed with Dravet syndrome (likely pathogenic/pathogenic variants in SCN1A) and two with Genetic Epilepsy with Febrile Seizures Plus (SCN1B)." (PMID 35886038, 2022). "GNDs with questionable or no response to antiparkinsonian medication in most cases were Rett syndrome, Dravet syndrome (SCN1A), phosphoglycerate kinase deficiency, dystonia 16, Leigh syndrome, and Menkes disease." (PMID 36699000, 2022). "SCN1A-related diseases have a wide range of clinical phenotypes, which are associated with a variety of epileptic types, such as febrile seizure and Dravet syndrome." (PMID 36237607, 2022).
Dravet syndrome (continued). "Subsequently, it was discovered that the vast majority of patients with Dravet syndrome harbored SCN1A variants with an increasing number of SCN1A variants being reported." (PMID 35571373, 2022). "Recent study has investigated that SCN1A T226M variant presents gain-of-function in early infantile development and epileptic encephalopathy which is far more severe than typical Dravet syndrome." (PMID 35571373, 2022). "Five of the decedent SUDEP cases had a diagnosis of Dravet syndrome with pathogenic variants identified in SCN1A gene." (PMID 34816733, 2021). "Dravet syndrome is typically caused by loss of function variants in the gene SCN1A, particularly affecting inhibitory interneurons." (PMID 34268891, 2021). "AntagoNATs effectively increased the expression of brain-derived neurotrophic factor (BDNF), a protein important in memory development, and the healthy allele of SCN1A, the haploinsufficiency of which triggers Dravet syndrome." (PMID 34899268, 2021). "Disease-causing variants in SCN1A are identified in up to 80% of individuals with clinical Dravet syndrome, and hundreds of individuals are diagnosed every year." (PMID 33411776, 2021). "Approximately 70–80% of Dravet syndrome patients have loss-of-function mutations in the sodium voltage-gated channel alpha subunit 1 (SCN1A) gene." (PMID 34335252, 2021). "Conversely, induced pluripotent stem cell–derived cardiomyocytes from patients with Dravet syndrome due to SCN1A mutations have abnormal contractility." (PMID 34930847, 2021). "An ASO-based strategy has been successfully used to enhance the expression of the WT Scn1a allele in a mouse model of Dravet syndrome in order to circumvent Nav1.1 haploinsufficiency." (PMID 34671263, 2021). "Scn1a+/− mice recapitulate several core features of Dravet syndrome, including spontaneous seizures, elevated risk of sudden death, and neurobehavioral and cognitive deficits." (PMID 34086081, 2021). "The therapeutic utility of such an approach was recently demonstrated for Dravet syndrome, where CRISPRa was used to upregulate the expression of the WT Scn1a allele by ~ 50%, and improved the epileptic phenotype." (PMID 34235638, 2021). "Pathogenic variants in the SCN1A gene are associated with a spectrum of epileptic disorders ranging in severity from familial febrile seizures to Dravet syndrome." (PMID 34938262, 2021). "It has been reported that parental mosaicism accounts for ~10% of de novo SCN1A (sodium voltage-gated channel alpha subunit 1) variants in children with Dravet syndrome." (PMID 34977057, 2021). "Variants of the SCN1A gene encoding the neuronal voltage-gated sodium channel NaV1.1 cause over 85% of all cases of Dravet syndrome, a severe and often pharmacoresistent epileptic encephalopathy with mostly infantile onset." (PMID 34925043, 2021). "In humans, loss-of-function mutations of its ortholog SCN1A are associated with Dravet syndrome, a rare and intractable childhood epilepsy." (PMID 33416493, 2021). "Taken together, these insights suggest much greater relevance of variants in SCN1A in a range of neurodevelopmental disorders extending beyond Dravet syndrome." (PMID 34925043, 2021). "The heterozygote loss of function of SCN1A in mouse is a model of Dravet syndrome and resembles many of the phenotypes observed in the family we analyzed." (PMID 34951628, 2021). "Dravet syndrome is a severe rare epileptic disease caused by mutations in the SCN1A gene coding for the Nav1.1 protein, a voltage-gated sodium channel alpha subunit." (PMID 34833136, 2021). "Second, glucose hypometabolism occurs in the brain of patients with Dravet syndrome with SCN1A mutations and zebrafish scn1lab mutants." (PMID 33842883, 2021). "First, noncoding de novo variants in highly conserved intronic regions of SCN1A were found in individuals with Dravet syndrome." (PMID 33411776, 2021). "The authors characterize a Dravet syndrome mouse model with a poison exon mutation resulting in aberrant Scn1a regulation." (PMID 33411776, 2021).
Dravet syndrome (continued). "SCN1A haploinsufficiency is the major cause of Dravet syndrome; therefore, mice with heterozygous deletion of Scn1a were developed to model Dravet syndrome." (PMID 34086081, 2021). "For instance, individuals with a clinical diagnosis of Dravet syndrome are likely to have a variant in a gene called SCN1A, and sodium-channel blockers should be avoided for treatment." (PMID 34827451, 2021). "Knock-in Drosophila lines were generated by CRISPR-Cas9 gene editing to explore how the R1648C (R-C) and R1648H (R-H) mutations in the SCN1A sodium channel gene contribute to distinct epilepsy disorders, Dravet syndrome, and GEFS+, respectively." (PMID 34475263, 2021). "Dravet syndrome is the result of mutations in the Scn1a gene which encodes the voltage-gated sodium channel Nav1.1." (PMID 34321997, 2021). "Some epileptic syndromes, such as Dravet syndrome (DS), are attributed to SCN1A mutations in approximately 80% of patients." (PMID 33333793, 2020). "Dravet syndrome (DS) is a refractory epilepsy typically caused by heterozygous mutations of the Scn1a gene, which encodes the voltage-gated sodium channel Nav1.1." (PMID 32184723, 2020). "The variant c.A2851G (p.M951V) in SCN2A occurred close to the selectivity filter, paralogous to SCN1A variants observed in Dravet Syndrome." (PMID 32666661, 2020). "Dravet syndrome (DS) is a neurodevelopmental genetic disorder caused by mutations in the SCN1A gene encoding the α subunit of the NaV1.1 voltage-gated sodium channel that controls neuronal action potential firing." (PMID 31830809, 2020). "1% (n = 6) of the overall cases were clearly identified as having Dravet syndrome or an SCN1A mutation." (PMID 32949224, 2020). "Among the genetic factors and in particular polymorphisms, the role of SCN1A gene mutations is demonstrated by the fact that the risk of post-vaccine seizures increased in patients with Dravet syndrome, a severe epileptic encephalopathy." (PMID 32269767, 2020). "SCN1A variants also account for 70–80% of Dravet syndrome (DS), a debilitating autosomal dominant infantile-onset epileptic encephalopathy." (PMID 33216760, 2020). "Mutations in the SCN1A gene, which encodes the voltage-gated sodium channel NaV1.1, lead to Dravet syndrome, which is characterized by temperature-sensitive epilepsy." (PMID 32264956, 2020). "More specifically, a mouse model of Dravet syndrome (Scn1a+/−) had previously been associated with a loss of excitability in PV+ and SOM+ cells, which both express Nav1.1." (PMID 32581726, 2020). "The importance of SCN1A gene mutation screening in severe epilepsy syndromes, such as Dravet syndrome is well established, however, the role of SCN1A variations in other phenotypes is not fully understood." (PMID 32581296, 2020). "VIP+ cells can also contribute to the pathogenesis of Dravet syndrome, a neurodevelopmental disorder associated with a loss of functional variants of the gene SCN1A that encodes for the Nav1.1 channel subunits." (PMID 32581726, 2020). "Case 3 identified a mutation in SCN1A (NM_001165963:c.680T>G:p.Ile227Ser) and was diagnosed as Dravet syndrome (OMIM:607208)." (PMID 33287870, 2020). "Dravet syndrome (DS) is an epileptic syndrome caused by mutations in the Scn1a gene encoding the α1 subunit of the sodium channel Nav1.1, which is associated with febrile seizures that progress to severe tonic-clonic seizures and associated comorbidities." (PMID 33584198, 2020). "Genetic variants in SCN1A have been associated with Dravet syndrome and other severe epileptic encephalopathies." (PMID 32722525, 2020). "1% (n = 6) of the overall cases were clearly identified as having Dravet syndrome (DS) or an SCN1A mutation." (PMID 32949224, 2020). "Our second patient had a heterozygous mutation c.3295G>T (p.Glu1099*) of the SCN1A gene, this mutation was already identified in patients showing Dravet syndrome." (PMID 31439038, 2019).
Dravet syndrome (continued). "In the Dravet syndrome cohort, SCN1A sequence variants were found in six patients, although Sanger sequencing performed before panel testing was negative in these patients." (PMID 31572294, 2019). "Another example is the autosomal-dominant SCN1A sodium channel mutation that underlies Dravet syndrome, a severe epileptic encephalopathy that begins in childhood." (PMID 30683131, 2019). "Modified proposed guidelines for combining different criteria to classify SCN1A missense variants in the context of the molecular diagnosis of patients with Dravet syndrome variants into “pathogenic” or “likely pathogenic” and correspondent scores." (PMID 31001185, 2019). "The incidence of Dravet Syndrome is 1 in 16,000 births, with most cases attributable to de novo SCN1A mutations." (PMID 30735520, 2019). "We observe elements of this interictal behavioral syndrome in seizure-prone DBA/2J mice and in mice with a pathogenic Scn1a mutation (modeling Dravet syndrome)." (PMID 31697745, 2019). "Sixteen predicted deleterious SCN1A variants found in our cohort of 21 patients with Dravet syndrome." (PMID 31001185, 2019). "Patients with Dravet syndrome (DS) possess the majority of SCN1A variants identified to date, with variants detected in 70–80% of these patients." (PMID 31001185, 2019). "Mutations in the SCN1A gene, which encodes for the voltage-gated sodium channel NaV1.1, cause Dravet syndrome, a severe developmental and epileptic encephalopathy." (PMID 30735520, 2019). "For SCN1A for example, a microdeletion in the 5’-promoter region was found in patients with Dravet syndrome, and another heterozygous mutation in the promoter region (h1u-1962 T >G) was identified in a patient with partial epilepsy and febrile seizures." (PMID 31992970, 2019). "Dravet Syndrome (DS) is a severe neurodevelopmental disorder caused by pathogenic loss of function variants in the gene SCN1A which encodes the voltage gated sodium (Na+) channel subunit Nav1.1." (PMID 31282864, 2019). "Dravet syndrome (DS) is a severe childhood-onset epilepsy commonly caused by mutations in the SCN1A gene." (PMID 30984098, 2019). "81.25% (13/16) SCN1A mutations were de novo in Dravet syndrome patients and one was inherited from the father who had a history of febrile seizures (FS)." (PMID 30185235, 2018). "Three variant were found in SCN1A, including two patients with Dravet syndromes (p.Leu890Pro, p.Arg1636Ter) and one family with genetic epilepsy with febrile seizure plus (GEFS+) (p.Met1714Val)." (PMID 30034362, 2018). "There has been a marked increase in genetic diagnoses of a number of key childhood-onset epilepsy syndromes, such as Dravet syndrome, which has been mainly linked to SCN1A." (PMID 30185235, 2018). "Previous studies have shown that patients with Dravet syndrome with SCN1A mutations respond well to KD, as did a patient with an SCN2A mutation who was treated with a modified Atkins diet." (PMID 30061856, 2018). "Identification of deleterious SCN1A mutations in five young infants with clinically suspected Dravet syndrome helped early diagnosis (Case 13, 38, 65, 115, 140) and led to the discontinuation of oxcarbazepine (Case 13) that exacerbated seizures." (PMID 30185235, 2018). "Identification of SCN1A mutations in other Dravet syndrome patients helped to avoid sodium channel blockers such as oxcarbazepine, carbamazepine and lamotrigine." (PMID 30185235, 2018). "All 18 Dravet syndrome patients were identified with mutations in SCN1A gene, and 14 (77.8%) patients showed a good response to KD at 3 months since initiation of KD." (PMID 30061856, 2018). "We describe two females who fulfill the diagnostic criteria for classic RTT, with pathogenic de novo mutations in SCN1A, which usually leads to Dravet syndrome." (PMID 30305042, 2018).
Dravet syndrome (continued). "In our 16 patients diagnosed as Dravet syndrome with pathogenic or likely pathogenic variants, all identified mutations were in the SCN1A gene." (PMID 30185235, 2018). "Patients harboring SCN1A mutations can have with Dravet syndrome or generalized epilepsy with febrile seizures plus." (PMID 30185235, 2018). "A genetic cause for an epileptic encephalopathy was first recognized in 2001, when all seven children who were recruited in a study of Dravet syndrome had a de-novo SCN1A mutation." (PMID 28387369, 2017). "For example, mutations in SCN1A (Nav1.1) are associated with Dravet syndrome, a severe myoclonic epilepsy of infancy, as well as West syndrome, genetic epilepsy with febrile seizures plus (GEFS+) and others." (PMID 28536506, 2017). "Mice heterozygous for a partial deletion of scn1a, or an scn1a nonsense variant, recapitulate the features of Dravet syndrome, including sudden death, and have been proposed as models of SUDEP." (PMID 28775708, 2017). "In Dravet syndrome, >80% of people have a variant in SCN1A, encoding a neuronal voltage-gated sodium channel alpha subunit 1, with 95% of 80 tested variants arising de novo." (PMID 28775708, 2017). "This study included the fixed postmortem tissue of one SUDEP in a person with Dravet syndrome in which the molecular autopsy identified a pathogenic SCN1A variant." (PMID 28775708, 2017). "Mice with global deletion of scn1a, or selective deletion of scn1a from the forebrain, have reduced heart rate variability, as in human Dravet syndrome, whereas scn1a deletion from the ventricles causes increased heart rate variability." (PMID 28775708, 2017). "With onset in the first year of life, de novo heterozygous missense mutations in SCN1A, which encodes the pore-forming α1 subunit of the sodium channel, are found in about 95% of patients with Dravet syndrome." (PMID 28197552, 2017). "We have identified a distinctive SCN1A developmental and epileptic encephalopathy that is far more severe than Dravet syndrome and is associated with a recurrent missense mutation." (PMID 28794249, 2017). "For example, experiments in a knock-in mouse model of Dravet syndrome have shown that the upregulation of the healthy allele of SCN1A by targeting a lncRNA improved the seizure phenotype." (PMID 28558813, 2017). "Truncation mutations in the voltage-gated sodium channel gene, SCN1A, usually result in Dravet Syndrome (DS)—a haploinsufficiency syndrome that includes severe progressive seizures and impaired cognition." (PMID 28686619, 2017). "In Dravet syndrome (DS), a mutation in SCN1A, coding for the voltage-gated sodium channel Nav1.1, is associated with severe cognitive impairment and seizures." (PMID 26978272, 2016). "This gain-of-function mechanism is opposite to the situation in Dravet syndrome, where loss-of-function mutations in SCN1A are most common." (PMID 27900360, 2016). "Initial insights into the neurobiological function of Nav1.1 came from studies of a mouse model of Dravet Syndrome, where the loss of one copy of Scn1a impaired the excitability of hippocampal inhibitory interneurons but not excitatory neurons." (PMID 27458797, 2016). "Mutations in the related sodium channel gene SCN1A contribute to Dravet syndrome, and mutations in SCN2A contribute to Ohtahara syndrome." (PMID 27900360, 2016). "SCN1A mutations related to Dravet syndrome include severe disruptions of channel integrity (e.g. frameshift mutations, deletions), and, less commonly, missense mutations leading to either channel impairment or gain of function." (PMID 27582020, 2016). "These cases confirm parental mosaicism in the transmission of Dravet syndrome and add to the spectrum of known mutations of the SCN1A gene." (PMID 27021235, 2016). "Our data present a case of Dravet syndrome caused by a novel heterozygous SCN1A deletion (c.1458_1465delCTCTAAGT) in two affected siblings." (PMID 27021235, 2016).